TMEM121 (transmembrane protein 121)
Description:
May play a role in MAPK signaling.
Synonyms: HHOLE; MGC4659; hole; TMEM121A
Tractability: Antibody: UniProt predicts a signal peptide or a membrane-spanning region.
Gene: Protein-coding gene on chromosome 14 (105,525,996 to 105,530,205, forward strand). Ensembl gene ENSG00000184986.
Subcellular location: Membrane
Subcellular location (Human Protein Atlas): Cytosol
Gene Ontology:
Molecular function: protein binding
Cellular component: membrane
Genetic constraint (gnomAD): Loss-of-function variants: 8 observed, 12.48 expected, observed/expected ratio (o/e) 0.64, 90% interval 0.38 to 1.16. The synonymous counts are far from expectation, so gnomAD's model fits this gene poorly and the ratio says little. Missense variants: 400 observed, 374.96 expected, observed/expected ratio (o/e) 1.07, 90% interval 0.98 to 1.16. Synonymous variants: 234 observed, 176.03 expected, observed/expected ratio (o/e) 1.33, 90% interval 1.19 to 1.48.
Homologues: Orthologues: chimpanzee TMEM121 (99% identical), macaque TMEM121 (99% identical), pig TMEM121 (98% identical), mouse Tmem121 (97% identical), dog TMEM121 (97% identical), guinea pig TMEM121 (93% identical), rat Tmem121 (86% identical), zebrafish tmem121aa (76% identical), zebrafish tmem121ab (75% identical), tropical clawed frog tmem121 (75% identical).
Diseases named in the same sentence as TMEM121 in open-access papers:
TMEM121 is named in the same sentence as 8 diseases in open-access papers, as found by Europe PMC text mining. Sharing a sentence is not in itself a finding about the gene and the disease. The quoted sentences say what the papers report.
psoriasis (1 paper, 2022). An autoimmune condition characterized by red, well-delineated plaques with silvery scales that are usually on the extensor surfaces and scalp. "Another study also indicated that TMEM121 plays a role in immunity related to skin diseases such as psoriasis." (PMID 35864541, 2022).
infection (1 paper, 2023). The state of being infected such as from the introduction of a foreign agent such as serum, vaccine, antigenic substance or organism. "For instance, the CR1 and TMEM121 loci have been shown to be adapted to pathogen infection in South China41." (PMID 37479695, 2023).
TMEM121 also shares sentences with these, for which no sentence is quoted: Astigmatism (1 paper); cancer (1); prostate carcinoma (1); spinocerebellar ataxia (1); tumor (1); xeroderma pigmentosum (1).